MAVS (mitochondrial antiviral signaling protein)
Diseases named in the same sentence as MAVS in open-access papers (continued):
Sharing a sentence is not in itself a finding about the gene and the disease.
infection (continued). "At 72 h post-infection, RT-qPCR, WB, and plaque assay showed that when TRIF, MAVS, and STING in IPEC cells were silenced by corresponding siRNA, N gene transcription, N protein expression, and virus replication levels of PEDV were slightly increased compared with the control group." (PMID 37631972, 2023). "The Western blotting results showed that TRIF, MAVS, and STING were most effective in inhibition, while MyD88, RIPK2, ASC, and CARD9-BCL10-MALT1 (CBM) were less effective in inhibiting N protein expression at 72 h post-infection." (PMID 37631972, 2023). "On the other hand, we have observed that the recovery of SERINC5 by anti-svRNA treatment during infection was accompanied by a greater increase in MAVS than that normally induced by SARS-CoV-2 infection alone, thus showing an accumulative effect." (PMID 36876111, 2023). "Similarly, at 24 h after infection with 100 HA/mL SeV, fixed mNG-RIG-I showed colocalization with immunolabeled MAVS." (PMID 36521492, 2023). "Along this line, others showed that upon infection with WNV no cytokine production was observed in MAVS-/-IFNAR-/- mice." (PMID 37720217, 2023). "qRT-PCR analysis of PEC derived from those mice revealed that MAVS-/-IFNAR-/- did not induce any IL-36γ mRNA upon RVFV cl13 infection while IFNAR-/- and MyD88-/-IFNAR-/- showed high levels of IL-36γ mRNA." (PMID 37720217, 2023). "Interestingly, ifnc was slightly induced in the NC and IRF7-1 KO with a smaller induction in the MAVS KO, as seen after SAV3 infection." (PMID 37588594, 2023). "In contrast, IRF3 and IRF7-1/3 KOs showed no elevated levels of these genes after infection, and, for the MAVS KO, induction was reduced compared to Wt." (PMID 37588594, 2023). "Furthermore, we proved that silencing of both svRNAs during the course of infection of Vero E6 cells restores SERINC5 expression and enhances the levels of its direct interacting partner, MAVS, a master protein involved in antiviral response." (PMID 36876111, 2023). "During the process of infection of invading cells, the innate immune pattern recognition receptor RIG-I can recognize the viral RNA in the invading cells and connect with the antiviral junction protein MAVS, which is localized in the mitochondria." (PMID 38005850, 2023). "Similarly, compared with control siRNA-treated cells, PEDV titers were obviously heightened in TRIF, MAVS, and STING siRNA-treated cells at 72 h post-infection." (PMID 37631972, 2023). "After 48 h of infection, LMH cells infected with FAdV-4 GY (group A) showed significant upregulation of the transcription levels of most immuno-cytokines (IL18, TLR7, IFN-α, and IFN-β excepted), such as OASL, Mx, MDA5, and MAVS." (PMID 37896849, 2023). "During infection, RIG-I dimerizes in an ATP-dependent manner and the activated multimeric form of RIG-I or MDA5 then interacts with the downstream adaptor protein mitochondrial antiviral signalling protein (MAVS, also known as CARDIF and IPS-1)." (PMID 35625186, 2022). "Interestingly, MAVS mRNA is elevated upon infection, suggesting that NSP5 reduces MAVS protein independently of its protease activity." (PMID 36146796, 2022). "Infection with SARS-CoV-1 also suppresses immune responses by targeting and degrading MAVS." (PMID 36300112, 2022). "RIG-I and its adaptor protein MAVS, two important mitochondrial antiviral proteins in the RIG-I-like receptor signaling pathway, can sense KSHV infection and suppress its replication following primary infection and/or viral reactivation." (PMID 36423164, 2022).
infection (continued). "When intracellular levels of RIG-I or its downstream effector MAVS were reduced by siRNAs in A549 cells, transfection of miR29b-1* no longer affected AdV-C5 infection compared to Rand transfected cells." (PMID 35891387, 2022). "Similarly, the mRNA expression of the MAVS and AZI2 was also elevated during most of the post-infection periods, except 24-, 120-, and 144 hpi." (PMID 36119061, 2022). "Knock-down of RIG-I, MDA-5, UNC93B1, MAVS or STING in THP1/CD169 macrophages did not impact infection efficiency of SARS-CoV-2, as shown by RT-qPCR analysis of viral gRNA and sgRNAs in each cell line." (PMID 36279285, 2022). "This led us to measuring Ifnb1 transcription at 16 h post-infection (or post-stimulation with KLA) in various IMM cell lines to determine the relative importance of TRIF, MAVS, and STING to the production of IFNβ at this critical stage following bacterial challenge." (PMID 33684179, 2021). "Similarly, compared with control siRNA-treated cells, the PRRSV titers were obviously heightened in TRIF, MAVS and STING siRNA-treated cells at 24 h, 48 h and 72 h post infection." (PMID 34696285, 2021). "The expression of MDA5, TANK and P-IRF3 protein decreased significantly (P < 0.01) after HEK-293 T cells infection with EMCV while the expression of MAVS and IRF3 protein showed no significant change." (PMID 34587973, 2021). "Agonist stimulation assay showed that MAVS and STING signaling possessed significant anti-PRRSV activities, whereas siRNA knockdown assay showed that TRIF, MAVS and STING are all involved in anti-PRRSV activity, with TLR3-TRIF displaying discrepancy in anti-PRRSV infection." (PMID 34696285, 2021). "The Western blotting results show that TRIF and MAVS are most effective in inhibition, MyD88, RIPK2, CBM and STING are intermediate in inhibition, and ASC is barely effective in inhibition of N protein expression at 48 h and 72 h post infection of PRRSV." (PMID 34696285, 2021). "Surprisingly, they did not suffer severe pathological damage in their tissues during infection, which was similar to what was found in animals lacking MAVS." (PMID 34503262, 2021). "A paper published by the Vidal lab reported that RIG-I, the PRR directly upstream from MAVS and responsible for its activation, as well as TLR3, responded to infection by another RNA virus, influenza A virus, through type 1 interferon signaling, resulting in a positive feedback loop." (PMID 34310619, 2021). "Our results showed that MAVS was degraded by aMPV/C infection in the presence of wortmannin (autophagy inhibitor) or CQ (lysosome inhibitor), suggesting that MAVS degradation by aMPV/C was not influenced by autophagy and lysosome pathway." (PMID 34696420, 2021). "Upon infection with RNA viruses, TBK1 is activated by the upstream protein MAVS, and activated TBK1 recruits IRF3 and IRF7; these proteins undergo TBK1-mediated C-terminal phosphorylation to trigger their dimerization and nuclear translocation, an event followed by induction of IFN secretion." (PMID 34782737, 2021). "An interesting finding that warrants further investigation is the observation that MAVS contributed to CXCL‐10 production in response to infection with DRV‐treated virus, but did not contribute to the corresponding IFIT‐1 reporter activity." (PMID 32852081, 2020). "The same infection experiment was performed in THP-1 cells with WSN WT and WSN ΔF to verify whether the diminishing effect of PB1-F2 on MAVS protein might be virus type-specific." (PMID 32511263, 2020). "This indicated a PB1-F2-mediated decrease in the level of MAVS protein in the early phase of infection with H7N9 but not WSN." (PMID 32511263, 2020). "In contrast, cells lacking either the type I IFN receptor (Ifnar1-/-) or MAVS failed to induce ISG expression upon infection and supported increased viral replication, indicating a dependence on RLR and type I IFN signaling for viral control." (PMID 32330200, 2020).
infection (continued). "Indeed, infection with EMCV-Lpro L92A, resulted in cleavage of eIF4G, as well as all other Lpro substrates (i.e. MAVS, TBK1, NF-κB p65 and G3BP1)." (PMID 32667958, 2020). "As RIG-I knockout and MAVS knockout cells do not significantly upregulate any genes following ΔPB1-mCherry infection, virus entry induces little response in vitro." (PMID 32790753, 2020). "In miiuy croaker brain cells (MBrC), MAVS-specific siRNA could also significantly suppress the expression of IFN-2, TNF-α, Mx1, and ISG15 upon SCRV infection." (PMID 32678830, 2020). "A study on mouse adapted EBOV (MA-EBOV) infection demonstrated that IFN-dependent and independent MAVS signaling takes place in an organ specific manner, where activation of monocytes and subsequent trafficking to the spleen occurs in a MAVS-dependent manner." (PMID 32983015, 2020). "Pekin duck MAVS is upregulated 1 DPI in both HPAI and LPAI infection in lungs, however no MAVS upregulation was seen in ileum of LPAI infected ducks." (PMID 32477965, 2020). "While control cells showed aggregation of MAVS only after RV infection, FOXO3a K/O cells showed MAVS aggregation under unstimulated conditions (sham infection), which did not increase after RV infection." (PMID 31796819, 2019). "However, in the early phase of post-infection, the CARMA3-BCL10 complex interacts with MAVS, therefore, preventing the formation of high-molecular weight MAVS aggregates that is required for downstream TBK1-IRF3 activation." (PMID 30814996, 2019). "As we observed robust GC responses after infection in the absence of MAVS, we next asked if T follicular helper cells (TFH), necessary to help affinity maturation of B cells in the germinal center, were also elevated." (PMID 31242236, 2019). "After infection with TGEV, UBXN1 is induced to recruit MAVS." (PMID 31029162, 2019). "The importance of RIG-I targeting for EBOV pathogenesis was illustrated by experimental infection of mice lacking expression of mitochondrial antiviral signaling protein (MAVS), a RIG-I adaptor protein.." (PMID 30791589, 2019). "During infection with DNA viruses, RNA polymerase III recognizes AT-rich dsDNA and transcribes the dsDNA into dsRNA containing a 5-triphosphate moiety that activates the RIG-I/MAVS pathway to induce IFN-β production." (PMID 32063900, 2019). "As STING, MAVS and TRAF3 were demonstrated to be key factors in regulation of that response, we aimed to quantify the variation in IFN-β transcripts in response to the infection." (PMID 29813068, 2018). "A comparison of expression after WNV infection to expression in subsets from uninfected mice revealed that as, expected, both Ddx58 and Ifih1 expression increased to varying degrees in several myeloid subsets after infection, but MAVS gene expression did not." (PMID 29408905, 2018). "Infection with SC35M clearly demonstrated that TRIM28 S473 was still phosphorylated in cells lacking the RIG-I downstream effector MAVS, which supported the previous results obtained in RIG-I KO cells (lane 7)." (PMID 30323812, 2018). "MAPL is not likely a part of the MAVS complex during infection, as the interaction with MAVS is lost at that time." (PMID 28273895, 2017). "First, MAVS was not completely cleaved in HAV-infected HepG2 cells in the early stage of infection (data not shown)." (PMID 28744018, 2017). "In addition, intrinsic MAVS signaling is dispensable for proper control of WNV, and further, appears not to be required for full Treg functional capacity following infection." (PMID 28094802, 2017). "Interestingly, DVG-mediated upregulation of TNFR2 signaling was controlled by MAVS, as MAVS KO cells showed impaired upregulation of surface TNFR2 expression and blunted expression of the pro-survival genes TRAF1, BIRC3, and TNFAIP3 upon infection with SeV HD." (PMID 28986577, 2017).
infection (continued). "We found that proteins critical to the function of Tregs such as CD73 and GITR (data not shown) were represented at similar frequencies despite a lack of MAVS expression in Tregs during infection." (PMID 28094802, 2017). "To determine if accumulation of DVG-high cells and death of FL-high cells depend on the antiviral response induced by DVGs9, 10, we analyzed infections of cells lacking the critical adaptor protein MAVS (MAVS KO) or lacking the type I IFN receptor (IFNAR1 KO)." (PMID 28986577, 2017). "Taken together, these findings demonstrate that RIG-I signaling through MAVS is critical for determining the quality of polyfunctional T cell responses against IAV and for providing protection against subsequent infection from heterologous or novel pandemic IAV strains." (PMID 27438481, 2016). "WT and MAVS-/- mice were adoptively transferred with CFSE labeled naïve OT-I CD8+ T-cells followed by intranasal infection with PR8 with or without endotoxin free ovalbumin (Ova) as an exogenous antigen." (PMID 27438481, 2016). "Through multiple techniques, we demonstrate that IL-10, PDL1 and iregDC generation are not specifically dependent on direct infection or recognition of intracellular viral replication by the LCMV sensors TLR3 or MAVS." (PMID 26808628, 2016). "mRNA of IFN-β and -λ1 was markedly induced at 12 h post-infection, but not in MAVS- and RIG-I-KD cells." (PMID 27560627, 2016). "That artificial activation of PKR was capable of inducing IFNβ in the absence of MDA5, but remained dependent on MAVS led us to conclude that it most likely acts during infection to transmit signals between these two elements of the pathway." (PMID 26939124, 2016). "To assess possible mechanisms of MyD88/TRIF/MAVS-independent resistance to RSV, we looked for indicators of antiviral activity and measured levels of IFN-γ and granzyme B in the airways (BAL fluid) at different time points after infection." (PMID 26688048, 2015). "Accordingly, the transcription factor IRF1, reported to be essential for MAVS-mediated IFNL1 expression, was detected in nuclear extracts as early as 6 h post infection with RSV-HD while it remained at basal levels in cells infected with RSV-LD or mock infected." (PMID 26336095, 2015). "As expected, in MAVS-/- MEFs without reconstituted MAVS no type I IFN was produced upon infection with SeV or reovirus." (PMID 26588843, 2015). "After infection, the C-terminal domain of RIG1/MDA5 undergoes a conformational change, driving a response through the mitochondrial antiviral signaling protein (MAVS), which serves as an adaptor in IFN signaling and is localized both at peroxisomes and mitochondria." (PMID 25664450, 2015). "However, at 8 hours post infection, depletion of STING partially reduced TNFα transcription induced by AdV+IgG, while depletion of MAVS reduced transcription upon infection with either AdV+IgG or HRV+IgG." (PMID 26506431, 2015). "Finally, recent reports have shown that MAVS plays a major role in virus-induced apoptosis, as for example by inducing caspase-3 activation upon Vesicular Stomatitis Virus (VSV) infection." (PMID 25738304, 2015). "In addition, MVA infection of human macrophages triggers type I IFN and pro-inflammatory cytokines and chemokines via a TLR2/TLR6/MyD88 and MDA5/MAVS-dependent pathways." (PMID 24743339, 2014). "The absence of RIG-I in the chicken genome imply that MAVS is probably less activated during infection and consequently reduce the negative effects of PB1-F2." (PMID 24959667, 2014). "Based on these results, we predicted that the absence of MAVS signaling in WNV-infected Mavs−/−×Ifnar−/− DKO mice would limit cytokine induction despite high levels of infection and viral RNA generation in permissive myeloid cells." (PMID 24743949, 2014). "Since A5-16 (NSP1 mutant), strain did not degrade MAVS; MAVS aggregates were studied followed A5-16 infection." (PMID 24643253, 2014).
infection (continued). "Despite translocation of bacRNA into the cytosol, RNAi of RIG-I or MAVS in monocytic cells (THP-1) did not impair type I IFN induction during infection with L. monocytogenes." (PMID 23653683, 2013). "Upon the transcript level analysis of the members in RLR family, up-regulation of RIG-I was evident within 6h of infection along with the up-regulation of its adaptor protein MAVS, where as there was no significant modulation in MDA 5 expression." (PMID 24086645, 2013). "This inhibition would be required by the virus only early during the course of infection because later in infection a viral protease, NS3/4A, cleaves the cellular protein, mitochondrial antiviral signaling protein (MAVS), which is required downstream of RIG-I to induce IFNα and β." (PMID 24710493, 2012). "Furthermore, not only for MAVS that is cleaved by DEN-2-induced caspases, the endogenous MITA protein levels were also reduced in cells with DEN-2 infection through an infection time- and infection dose-dependent manner." (PMID 22761576, 2012). "A degradation of the larger MAVS isoform occurred following SeV H4, but not WT, infection, implying that MAVS is not cleaved by a specific SeV protease." (PMID 22626058, 2012). "Both MAVS and TRAF3, but not RIG-I, associate with PKR in a time dependent manner, beginning at 2 hrs post-infection." (PMID 22022264, 2011). "The kinetics of MAVS cleavage was also not consistent with apoptosis: MAVS cleavage was evident by 3 hrs post-infection (p.i.)whereas apoptosis (as measured by caspase-3 cleavage) did not occur until 5–6 hrs p.i.." (PMID 21436888, 2011). "Although infection of cells with CVB3 is sensitive to IFNβ, we observed less enhancement of IFNβ promoter activity as assessed by luciferase activation in CVB3-infected HEK293 cells overexpressing MAVS, MDA5, RIG-I, and TLR3/TRIF than in uninfected controls." (PMID 21436888, 2011). "To determine whether γHV68 infection altered MAVS expression, we infected BL/6 mice intranasally with a high dose (1×105 PFU) of γHV68, presumably permitting synchronized and maximal infection of lung epithelial cells." (PMID 20686657, 2010). "Plaque assays and multi-step growth curves of γHV68 lytic infection showed that deficiency in TRAF6, IKKγ, and IKKβ, but not deficiency in the closely related IKKα, recapitulated phenotypes of MAVS deficiency." (PMID 20686657, 2010). "PKR silencing, as well as treatment with PKR pharmacological inhibitors, restored IFN induction in JFH1-infected cells, at least until 18 hrs post-infection, at which time a decrease in IFN expression could be attributed to NS3/4A-mediated MAVS cleavage." (PMID 20485506, 2010). "Similarly, early infection with dengue virus (DENV), another member of the Flaviviridae family, induces the ATG5-ATG12 conjugate, which attenuates MAVS-mediated IFN-stimulated gene expression, thereby helping the virus evade antiviral response prior to IFN signaling activation." (PMID 41363843, 2026). "Notably, this interaction was significantly enhanced after IAV-H1N1 or IAV-H3N2 infection, without altering the mRNA level of MAVS, suggesting that TRIM22 promoted the antiviral response through interaction with MAVS." (PMID 40162781, 2025). "However, more recently NLRX1 has been shown to also regulate apoptosis through mechanisms that are independent of RIG-I/MAVS and NF-κB following infection with influenza virus." (PMID 40356929, 2025). "Importantly, our study also highlighted MAVS and MDM2 genes with common DRE sites across different ocular SARS-CoV-2 infections, pointing to common regulatory mechanisms in these tissues during the infection." (PMID 38693480, 2024). "The results showed that the expression of MAVS, IRF7, STING, NF-κB, MAD5, LGP2, IFN-α and IFN-β was upregulated compared with that in the control group, regardless of whether IFITM3 was overexpressed or inhibited after infection." (PMID 38543696, 2024).